CEBPA (CCAAT enhancer binding protein alpha)
Diseases named in the same sentence as CEBPA in open-access papers (continued):
Sharing a sentence is not in itself a finding about the gene and the disease.
leukemia (continued). "For example, our final causal gene set included GBAS (for its causal network), a gene that was reported amplified in more than 40% of glioblastomas and CEBPA (enhancer binding protein) that was amplified in about 10% of leukemia cases." (PMID 21390271, 2011). "This interaction was found to be crucial for maintaining CEBPA gene expression in leukemia cells." (PMID 40265378, 2025). "Categories with acute megakaryoblastic leukemia (AMKL) or acute erythroid leukemia (AEL) phenotypes are clearly enriched in infants, whereas CBF leukemias and mutation-defined leukemias (for example, UBTF, NPM1, CEBPA) were enriched in adolescents and young adults." (PMID 38212634, 2024). "Interestingly, CEBPA itself is understood to represent a tumor suppressor gene, particularly in leukemia." (PMID 38442712, 2024). "Furthermore, Gata2 V2 levels were decreased, and Gata2 V2 promoter DNA methylation was increased upon Cebpa depletion in an MLL-AF9 leukemic setting where CEBPA is dispensable for maintenance of the leukemia." (PMID 37794021, 2023). "Moreover, through targeting the FTO/MYC/CEBPA axis, R-2HG inhibited the proliferation of leukemia cells." (PMID 35186927, 2022). "In addition, the metabolite R-2HG caused by isocitrate dehydrogenase (IDH) mutation exerts anti-leukemic effects by inhibiting FTO/m6A/MYC/CEBPA signaling, providing a new target for clinical dosing in the treatment of leukemia." (PMID 36118041, 2022). "Likewise, targeting FTO/MYC/CEBPA signaling, R-2HG displays an intrinsic and broad anti-tumor activity in leukemia." (PMID 36035161, 2022). "Importantly, R-2HG exhibited a potent anti-tumor effect against leukemia with high FTO expression by targeting FTO-m6A-MYC/CEBPA axis." (PMID 35859892, 2022). "Moreover, it increases m6A modification of RNA by inhibiting FTO activity, destabilizing CEBPA/MYC transcripts in leukemia cells." (PMID 35186927, 2022). "Furthermore, the persistence of leukemia-associated mutations, such as FLT3-ITD, NPM1, and CEBPA mutations, after the initial course of standard induction chemotherapy imparts a significantly increased risk of subsequent leukemic relapse and death." (PMID 34422653, 2021). "The aim of the study was to evaluate CEBPA and c-MYC mRNA expression level and to seek their association with demographical and clinical features of AML patients such as: age, gender, FAB classification, mortality or leukemia cell karyotype." (PMID 33170359, 2020). "Given our promising results demonstrating uptake of RNA via liposomes in a mouse PDX model, we sought to explore whether systemic administration of MTL-CEBPA could upregulate CEBPA expression in human leukemia cells engrafted in the bone marrow and spleen of mice." (PMID 40686853, 2025). "Overall ALL cases show lower CEBPA transcript levels, this seems to sustain the hypothesis that both a reduction and increase in gene dosage may be involved in the pathogenesis of various leukemia types." (PMID 31666608, 2019). "Based on the existing data showing the aberrantly low expression of the CEBPA gene in patients with acute leukemia harboring the CALM/AF10 fusion gene, we decided to evaluate in vivo if haploinsufficiency of CEBPA predisposes CALM/AF10+ hematopoietic cells to develop leukemia." (PMID 31141090, 2019). "An example is the myeloid transcription factor CEBPA: while under normal conditions it functions as a typical tumor suppressor and master regulator of myelopoiesis, it has been reported that its expression is crucial for mixed lineage leukemia (MLL) rearrangements to induce leukemia in mice." (PMID 28081132, 2017).
leukemia (continued). "Both FB23 and FB23-2 suppress leukemia progression by selectively blocking FTO and restoring the m6A profile of MYC, CEBPA, RARA, and ASB2 genes." (PMID 41157107, 2025). "Remarkably and unexpectedly, a single node in this network, a MECOM-bound cis-regulatory element located 42 kilobase (kb) downstream of the myeloid differentiation regulator CEBPA is both necessary and sufficient for maintaining MECOM-driven leukemias." (PMID 40991835, 2025). "Current clinical studies on saRNAs primarily focus on the transcriptional activation of the CCAAT/Enhancer Binding Protein Alpha (CEBPA, or C/EBPα) gene for the treatment of leukemia and solid tumors." (PMID 40422200, 2025). "CS1 and CS2 demonstrated suppression of leukemia proliferative activity and immune evasion, cancer cell viability, and leukemia stem cell renewal via MYC, CEBPA, and RARA axis." (PMID 41157107, 2025). "The use of small-molecule inhibitors targeting FTO affected the expression levels of downstream genes such as MYC, CEBPA, RARA, and ASB2, thereby exerting anti-leukaemia effects." (PMID 39641872, 2024). "Altogether, our work proposes that CEBPA-mutant AMLs acquire additional lesions in genes such as GATA2 and TET2 to reestablish balanced GATA2 levels that permit leukemia development and progression." (PMID 37794021, 2023). "For example, R-2-hydroxyglutarate (R-2HG), produced by mutant isocitrate dehydrogenase 1/2 enzymes, was recently found to be able to restrain leukemia cell proliferation and induced cell apoptosis by targeting FTO/m6A/MYC/CEBPA signaling." (PMID 33611339, 2021). "R-2-Hydroxyglutarate (R-2-HG) can also inhibit FTO activity, thereby increasing the m6A RNA modification in R-2HG-sensitive leukemia cells, reducing the stability of MYC/CEBPA transcripts, and leading to the inhibition of related pathways." (PMID 34858499, 2021). "This raises the question of how, and in which cell type, synergy between CEBPA and GATA2 mutations is achieved, and in particular whether the bilineage leukemia phenotype is maintained by a single bipotent, or by two distinct lineage-restricted, leukemia-propagating cell populations." (PMID 32330454, 2020). "Most recently, it has been reported that FTO plays a carcinogenic role through the FTO/m6A/MYC/CEBPA signaling pathway in IDH mutant cancers, such as glioma and leukemia." (PMID 32211315, 2020). "For example, YTHDF2 facilitated c-MYC and CEBPA mRNA degradation by binding to the m6A site in 5'UTR and coding region of c-MYC and CEBPA mRNA, resulting in leukemia cell proliferation." (PMID 32850334, 2020). "R-2HG can inhibit leukemia and glioma through the regulation of R-2HG-FTO-m6A axis to MYC/CEBPA expression and downstream pathways." (PMID 33304380, 2020). "AI-10-49 is of particular interest for treatment of (inv16) AML as it inhibits RUNX1 binding to CSF1R, RUNX3 and CEBPa promoter targets and also strongly increases mice survival in CBFβ-MYH11 murine leukemia cell models by reducing leukemia burden." (PMID 29921764, 2018). "Another regulatory link identified as an important discriminator between the two types of leukemia, with a score just below this cutoff, involves the C/EBP alpha (CCAAT/enhancer binding protein, CEBPA) regulating PPAR-gamma (PPARG)." (PMID 16670008, 2006). "In FTO high cancer cells, including leukemia and glioma, R-2HG inhibited cancer cell proliferation/survival and promoted cell cycle arrest and apoptosis, while reversing drug resistance by targeting the FTO/m6A/MYC/CEBPA signaling pathway." (PMID 41362736, 2026).
leukemia (continued). "In keeping with this, CIMP leukemias also exhibited increased methylation at NOTCH1, MYB, and TAL1 binding sites than ETP-ALL, and hypomethylation of TFBS for myeloid master regulators such as CEBPA, CEBPB, and SPI1." (PMID 38972954, 2024). "We hypothesize that CIMP and CEBPA-silenced leukemias are the same entity, hereinafter referred to as CIMP leukemias." (PMID 38972954, 2024). "Besides, some of the DMRs with the strongest increases were adjacent to genes such as CEBPA, LEF1, PLK2, MEIS1 or TLE4, which have a known involvement in either leukemia or hematopoiesis." (PMID 38972954, 2024). "Moreover, binding sites for hematopoietic transcription factors, including CEBPA, SPI1 and LEF1, are uniquely inaccessible in these leukemias." (PMID 38972954, 2024). "FTO expression was suppressed by R-2HG treatment in sensitive leukemia cells through downregulation of CEBPA transcription factor but not in resistant cells." (PMID 37161388, 2023). "R-2-Hydroxyglutarate (R-2HG) directly binds to the FTO (which participates in the m6A process) and inhibits its activity, thereby reducing the m6A modification and stability of c-MYC and CEBPA in the 5′-UTR and coding regions, leading to apoptosis of leukemia cells." (PMID 34858499, 2021). "Finally, we performed xenotransplantation of electroporated primary AML cells into nonirradiated immunodeficient NBSGW mice to assess how CEBPA cisRE activation impacts leukemia burden and engraftment of modified cells." (PMID 40991835, 2025). "Additionally, FTO can enhance the stability of MYC and CEBPA mRNA, thereby promoting cell proliferation, and METTL14 and YTHDF2 promote the self-renewal of leukaemia stem cells (LSCs)/leukaemia initiating cells (LICs), while ALKBH5K promotes LSC proliferation and induces apoptosis." (PMID 39641872, 2024). "In light of these findings, we asked whether elevated CEBPA level and not the CEBPA mutation(s) per se, drives the selective pressure for GATA2 and/or TET2 loss in AML to achieve moderate GATA2 levels that are optimal for leukemia growth." (PMID 37794021, 2023). "Accordingly, whereas most leukemia and lymphoma cell lines tested were not able to transdifferentiate in an efficient manner, BLaER1 cells are able to efficiently undergo the process, likely due to the constant and high expression levels of transgenic CEBPa." (PMID 35619054, 2022). "Thus, FTO could be suppressed by R-2HG in sensitive leukemia cells to elevate global m6A RNA modification, which destabilizes the MYC/CEBPA transcripts and reduces their expression." (PMID 31921664, 2019). "However, when Cebpα is ablated in already existing leukemia in vivo, it does not change the overall survival or immunophenotype of these animals, this indicates that C/EBPα is not required for maintenance of MLL-ENL AML cells but has a defined role during leukemogenesis." (PMID 36969082, 2023).
hepatocellular carcinoma (59 papers, 2006 to 2025). A malignant tumor that arises from hepatocytes. "After showing increased expression of CEBPA mRNA in white blood cells after administration in patients, MTL-CEBPA is about to enter in a phase II clinical trial for hepatocellular carcinoma caused by a hepatitis B and/or C infection." (PMID 35213992, 2022). "CEBPα cooperating with Sp1 was reported to induce miR-122 expression by binding to its promoter in hepatocellular carcinoma cells, and miR-122 is a potential therapeutic target for the treatment of liver disease." (PMID 36747241, 2023). "To date, there is a single saRNA candidate that has progressed into clinical trials, targeting the CEBPA gene in hepatocellular carcinoma (HCC)." (PMID 36700046, 2022). "MTL-CEBPA is a small activating RNA drug which upregulates gene expression of CEBPA for treatment of hepatocellular carcinoma (HCC)." (PMID 34502076, 2021). "MTL-CEBPA, designed to upregulate transcription of the CEBPA gene, is in clinical trials in advanced hepatocellular carcinoma." (PMID 33996898, 2021). "MTL-CEBPA, a first-in-class compound that reverses CEBPA downregulation in oncogenic processes using CEBPA-51 saRNA has entered clinical trial for the treatment of hepatocellular carcinoma (HCC)." (PMID 34770939, 2021). "The overexpression of CEBPA is significantly correlated with the poor prognosis of ovarian cancer and hepatocellular carcinomas (HCCs), indicating its oncogenic role in these neoplasms." (PMID 32695658, 2020). "A negative correlation between secreted IL-6 and SC adipogenic capacity was apparent, perhaps consequent to IL-6 repression of CEBPα expression in hepatoma cells." (PMID 27342408, 2016). "In a gene expression profiling studies with primary human hepatocytes and human hepatoma cell lines a Matrigel sandwich configuration retained abundant expression of LETFs such as CEBPα and HNF4α." (PMID 25901575, 2015). "In an analysis of patients with hepatocellular carcinoma treated with MTL-CEBPA and sorafenib, we observed a trend of CEBPA mRNA upregulation associated with outcome, though we did not detect an association between CEBPA mRNA upregulation with outcome in TIMEPOINT." (PMID 40168999, 2025). "Similarly, it has been reported that upregulation of CEBPA expression using saRNA slows the growth of rapidly proliferating hepatoma cells." (PMID 34770939, 2021). "Moreover PR11 and PR-1611 activate the PR gene in breast cancer cells, and CEBPA-saRNA activates the CEBPA gene in hepatocellular carcinoma cells." (PMID 34537818, 2021). "In a hepatocellular carcinoma (HCC) cell line transfected with MTL-CEBPA, increased levels of both CEBPA and albumin mRNA in addition to a 3-fold increase in albumin secretion and 50% decrease in cell proliferation was observed." (PMID 34502076, 2021). "For example, radiological regression of tumors using saRNAs reverse downregulation of CCAAT/Enhancer Binding Protein Alpha (CEBPA) and is effective in patients with advanced hepatocellular carcinoma." (PMID 40985895, 2025). "Currently, in clinical trials, the first saRNA treatment (MTL-CEBPA) targets and up-regulates the myeloid transcription factor CCAAT enhancer binding protein (CEBPA) in advanced hepatocellular cancer." (PMID 39179585, 2024). "Similarly, studies on human hepatocellular carcinomas (HCC) showed up-regulation of CEBPA at both mRNA and protein levels." (PMID 27602952, 2016). "The CEBPA gene is regulated by histone deacetylation (and slightly increased with 5-aza-dC and TSA) in the HepG2 human hepatoma cell line." (PMID 16854234, 2006). "Next, we compared binding profiles of CEBPA enhancers between the CEBPA-expressing hepatocellular carcinoma (HCC) cell line HepG2 and non-CEBPA-expressing cell line HeLa by aligning ChIP-seq tracks (ENCODE) of H3K27ac, Pol II, Pol II Ser2, p300, and CEBPB." (PMID 34039742, 2021).
breast cancer (48 papers, 2006 to 2025). A primary or metastatic malignant neoplasm involving the breast. "In 4w-11 tumors, CEBPA, which is associated with breast cancer progression was down-regulated and CEBPB, a gene found to be up-regulated in breast cancer as well as mouse mammary tumors, is up-regulated." (PMID 17147824, 2006). "It has been reported that CEBPA (C/EBPα) is a Smad3-repressed target during TGFβ-induced EMT in human breast cancer." (PMID 36785790, 2023). "Research by Lourenço and Coffer showed that the downregulation of CEBPA expression had been confirmed in a variety of solid tumors, such as liver cancer, breast cancer, and lung cancer." (PMID 35284484, 2022). "ARID1A is a key neoplasm suppressor gene that cooperated with CEBPα inhibited UCA1 transcription in breast cancer." (PMID 33592583, 2021). "As for solid tumors, CEBPA protein expression was reported to be markedly diminished in lung, skin and breast cancers." (PMID 27602952, 2016). "To determine the role of the accumulated lipids in macrophages, we noticed that FABP4 expression was not only associated with the LA/CEBPα/DGAT-mediated lipid accumulation pathway, but also highly correlated with the β-AR/ATGL/HSL-mediated lipolysis pathway in breast cancer." (PMID 39513934, 2024). "Furthermore, the breast cancer patients’ survival probability in high methylated CEBPA group was dramatically lower than that in low methylated CEBPA group, based on the best critical prognostic index analysis of a database from SurvivalMeth." (PMID 38102722, 2023). "Interestingly, VD induced CEBPα in breast cancer MCF-7 cells and CEBPα knockdown suppressed VD anti-proliferative effects." (PMID 34680392, 2021). "Furthermore, recent studies have demonstrated that demethylating agents induce VDR expression in AML and in high CEBPα breast cancer cells." (PMID 34680392, 2021). "Importantly, our observations are supported by clinical data of breast cancer patients where CEBPA expression is found higher in primary normal tissue compared with primary tumor and markedly lower in primary tumors with metastasis compared with primary tumor without metastasis." (PMID 32034145, 2020). "These known targets included CEBPα, STK40, and E2F2 which had been shown to be downregulated at mRNA level by miR-31-H in ovarian cancer cells and Frizzled3 (Fzd3) and MMP16 which were repressed at the protein level by miR-31 in MDA-MB-231 breast cancer cells." (PMID 23472152, 2013). "Moreover, CEBPα modulates vitamin D signaling in hematopoietic, AML and breast cancer cells." (PMID 34680392, 2021).
lung carcinoma (35 papers, 2006 to 2025). "But the pathologic mutations of CEBPA were uncommon in lung cancer." (PMID 34970478, 2021). "LOXL2 was shown by Fan and colleagues to promote lung cancer metastasis and progression via CEBPA‐mediated upregulation, which inhibits BCL‐2 degradation." (PMID 41395115, 2025). "Interestingly, not only the three TFs involves lung cancer development, but also CEBPA plays an important role in cell cycle." (PMID 25198518, 2014). "CEBPA can recruit Tip60, thereby enhancing the transcription of LOXL2 and LOXL3 and the histone acetylation process in lung cancer cells." (PMID 41250755, 2025). "In lung cancer, CEBPA enhances the transcriptional expression of LOXL2/LOXL3 and stabilizes BCL-2, thereby promoting the initiation and progression of lung cancer." (PMID 41250755, 2025). "Unlike hematopoietic cells, the human lung cancer cell line H358 did not exhibit any changes in the cell cycle upon transfection with CEBPA, and the CEBPA transgene stimulated apoptosis only in the context of toxic stimulation by zinc." (PMID 23437297, 2013). "Finally, CEBPA binds to Tip60 to promote the transcription of LOXL2 and LOXL3, thereby enhancing the stability of BCL-2 and ultimately promoting the development and metastasis of lung cancer cells." (PMID 41250755, 2025).
Insulin resistance (32 papers, 2013 to 2026). Increased resistance towards insulin, that is, diminished effectiveness of insulin in reducing blood glucose levels. "Moreover, FLRE and FLLE remarkably reduced chemoattractant (MCP-1) but improved adipogenic (PPARγ and CEBPα) gene expression, leading to the promotion of adipogenesis and the suppression of insulin resistance." (PMID 38543073, 2024). "Additionally, reduced CEBPA expression, which plays a pivotal role in adipocyte differentiation, intensifies metabolic disorders and leads to abnormal lipid storage, further contributing to the development of insulin resistance." (PMID 40806527, 2025).
Hepatic steatosis (30 papers, 2014 to 2025). Steatosis is a term used to denote lipid accumulation within hepatocytes. "Hepatic CEBPA was suggested to promote hepatic lipogenesis, while hepatocyte CEBPA knockout potentiated fatty liver in some currently examined experimental MASH conditions, raising new concerns regarding the lipid-lowering role of hepatocyte CEBPA." (PMID 38557493, 2024). "Here, myeloid-FATP4 deficiency may promote male-prone abnormalities by exacerbating hepatic steatosis possibly via the strong activation of PPARγ, CEBPα, and p-FoxO1 in their Kupffer cells." (PMID 36881564, 2023). "In contrast, inhibition of CCAAT enhancer binding protein alpha (C/EBPα) or Yin Yang 1 (YY1) activation can improve glucose metabolism and hepatic steatosis." (PMID 39911797, 2025).